EGFR (epidermal growth factor receptor)
Diseases named in the same sentence as EGFR in open-access papers (continued):
Sharing a sentence is not in itself a finding about the gene and the disease.
breast tumors (continued). "Our MCTS-laden HAGM cryogel platform could be leveraged as an in vitro tool to further investigate the role of HA on promoting epidermal growth factor receptor (EGFR)-mediated signaling pathways as well as breast tumor metastasis and chemoresistance." (PMID 35198956, 2022). "Targeting proteolytic neoepitopes may serve as an orthogonal “AND” gate for enhancing the therapeutic index, an observation even more clinically important as EGFR/RAS pathway activation is prevalent in breast tumors with poor prognosis." (PMID 35885460, 2022). "For example, a fusion of the platelet derived growth factor receptor transmembrane domain and an epidermal growth factor receptor (EGFR)‐targeting peptide is expressed from a retroviral plasmid in HEK‐293T cells to produce EGFR‐targeting EVs that deliver anti‐cancer let‐7 to breast tumours." (PMID 33643546, 2021). "The induction of EGFR under hypoxic conditions has been found to promote cell proliferation and migration, and patients with hypoxic breast tumors and EGFR hypomethylation may benefit from EGFR inhibition." (PMID 34228637, 2021). "As a proof of principle in an orthogonal mammalian system dependent on EGFR for morphogenesis, we employed the human breast tumour cell line HMT3522 T4-2 (henceforth referred to as ‘T4-2’) as a paradigm to test the role of mammalian RAL GTPases in malignant growth." (PMID 34096503, 2021). "Similar to ERRα loss-of-function in BC cells, SKBR3 cells treated with lapatinib, a dual epidermal growth factor receptor (EGFR)/human EGFR-2 (HER2) tyrosine kinase inhibitor approved for patients with HER2-amplified breast tumors, decreased both ERRα and DNMT1 protein levels." (PMID 32855526, 2020). "Proteome-based networks distinguish functional protein modules for breast tumor groups, with co-expression of EGFR and MET marking ductal carcinoma in situ regions of normal-like tumors and lending to a more accurate classification of this poorly defined subtype." (PMID 30962452, 2019). "Given that activation of RasGRF2 by Ca2+ mobilizing oncogenes constitutes an important axis for Ras activation by several RTKs and GPCRs, this study provides a strong rationale to target these hard-to treat breast tumors with EGFR targeted therapies in combination with inhibition of RasGRF2." (PMID 30719209, 2019). "We showed previously that PIPKIγ could be phosphorylated by EGFR at Y649, which is critical for the directional migration and metastasis of breast tumor cells." (PMID 28388589, 2017). "In addition, the strongest correlation is confirmed between the EGFR-positive breast tumor and lung metastases, and as many as 75.8% of all those patients whose first distant recurrence was in the lung had either EGFR-positive or HER2-positive." (PMID 28427196, 2017). "EDIL-3 could activate EGF receptor (EGFR) signaling to promote bladder cell migration, and lysyl oxidase secreted by hypoxic breast tumor cells was considered to be a crucial mediator of pre-metastatic niche formation." (PMID 28706483, 2017). "As expected, EGFR overexpression markedly increased breast tumor growth." (PMID 28703807, 2017). "Additionally, these studies will be essential to confirm if IKKε can be used as a biomarker to define personalized prognostic and the potential of targeting IKKε for therapeutic opportunities, particularly in EGFR+ breast tumors." (PMID 28532474, 2017). "The correlation between CD47 and EGFR expression in human breast tumors suggests that therapeutic CD47 antibodies may be effective against tumors with high EGFR expression when used alone or in combination with EGFR inhibitors." (PMID 26840086, 2016). "Alterations in estrogen signaling pathways in ERα+ breast tumors can arise from increased growth factor signaling, such as epidermal growth factor receptor (EGFR) and AKT/mammalian target of rapamycin (mTOR) pathways, and more recently to ERα isoform variation." (PMID 29657266, 2016).
breast tumors (continued). "GI-101A is an estrogen-receptor and EGFR-positive, basal-like low metastatic cell line derived from a primary infiltrating ductile breast tumor and its counterpart GI-LM2 is a highly metastatic variant that was isolated from repeated lung metastasis of GI-101A." (PMID 27687248, 2016). "In both cell lines and primary patient samples, we observed consistent expression patterns of these biomarkers varies by cancer indication, such that ERBB3 and CDKN1B expression are relatively high in breast tumors while EGFR expression is relatively high in other indications." (PMID 27035903, 2016). "Overall, the association between EGFR amplification and ER-negative status suggest that EGFR signaling pathway may play a role in male breast carcinogenesis, mainly in estrogen-insensitive breast tumors." (PMID 27765917, 2016). "EGFR plays a crucial role in the breast tumor growth and metastasis." (PMID 26025929, 2015). "This class of agents might be useful in the treatment of HER2- and EGFR-dependent breast tumors and may be effective for the treatment of cancers that have acquired resistance to monoclonal antibodies or tyrosine kinase inhibitors targeting these enzymes." (PMID 25865227, 2015). "We postulated that the TKI-associated change in the EGFR homodimer kinetics could directly impact the signaling property of the EGFR signaling network on the plasma membrane and hence the proliferative activity of the breast tumor cells." (PMID 25762314, 2015). "In the HMT-3522-T4-2 cells, EGFR and β1 are upregulated, and inhibition of EGFR or β1 by blocking antibodies and other inhibitors induces downregulation of EGFR expression and phosphorylation in parallel with the reversion of breast tumor cells to a phenotypically normal morphology." (PMID 25606594, 2014). "Although we did not extend such analyses to all patients, it appears that mutational events, such as loss of heterozigosity, are not affecting the EGFR locus of breast tumors." (PMID 24629097, 2014). "Basal-like breast tumors are preferentially low in ER and HER2 expression, and are significantly associated with several basal cytokeratin (CK) markers, including CK5/6, CK14, CK17, and the epidermal growth factor receptor (EGFR)." (PMID 24340082, 2013). "Western blot analysis using lysates of subcutaneous MDA-MB-468 breast tumors after different treatments was performed to evaluate whether the nanobioconjugate with AON inhibits EGFR expression and its related signal." (PMID 22355336, 2012). "In this study we used BLI to monitor the kinetics of tumor cell death after PIT in epidermal growth factor receptor (EGFR) expressing orthotopic breast tumors after the mouse received anti-EGFR panitumumab-IR700 conjugate (Pan-IR700) followed by varying intensities of NIR light." (PMID 22873679, 2012). "Basal-like breast tumors are preferentially low in ER and HER2 expression, and are significantly associated with several basal cytokeratin (CK) markers, including CK 5/6, CK 14, CK 17, and epidermal growth factor receptor (EGFR)." (PMID 23049873, 2012). "It appears that positive EGFR protein expression does not predict the presence of mutations in triple negative breast tumours; conversely, mutations have been found in negative EGFR immunostained breast tumours." (PMID 21457545, 2011). "Since we found no incidence of oncogenic KRAS mutations in basal-like tumors, our results indicates that therapies based on EGFR inhibition may be of benefit in the treatment of this particularly agressive subtype of breast tumors." (PMID 20385028, 2010).
breast tumors (continued). "This study indicates that KRAS mutations are very infrequent in triple-negative breast tumors and that EGFR inhibitors may be of potential benefit in the treatment of basal-like breast tumors, which overexpress EGFR in about 60% of all cases." (PMID 20385028, 2010). "About 20–40% of breast tumors have been reported to be positive for EGFR." (PMID 19416474, 2009). "The relationship between EGFR and/or ErbB2 overexpression, MAPK hyperactivation, NF-κB transcriptional activity and loss of ER protein expression in Basal-like or ErbB2-overexpressing breast tumours is currently under investigation." (PMID 17700572, 2007). "In this context, we have shown that the NF-κB signature performed better in separating ER-negative breast tumours from ER-positive breast tumours as well as EGFR- and/or ErbB2-overexpressing breast tumours from their EGFR-negative and ErbB2-negative counterparts." (PMID 17848951, 2007). "EGFR is an important regulator of epithelial cell biology, but its function in breast tumors is complicated by the observation that its function may vary according to important clinical features like estrogen receptor (ER) and HER2 status." (PMID 17663798, 2007). "In this study, we hypothesized that the breast tumor "intrinsic" subtypes might vary in dependence upon EGFR-signaling, which could be reflective of differences in gene expression patterns." (PMID 17663798, 2007). "Interestingly, in human bronchial and breast tumor cells, blocking the ionization-induced nuclear import of EGFR by the use of anti-EGFR antibodies increased radio-sensitivity of treated cells, by sequestering DNA-PK in the cytoplasm, complexed to EGFR." (PMID 17049074, 2006). "ANXA1 binds to cell membrane phospholipids and can be phosphorylated by the epidermal growth factor receptor, TRPM7 channel kinase 1, protein kinase A and protein kinase C. Its expression has been linked to carcinogenesis and metastasis in various tumor types, including breast tumors." (PMID 39040439, 2024). "However, there is a wide range of levels of expression of EGFR in the various breast tumors, and no clear association has been detected between the level of expression of EGFR and the sensitivity to GEF." (PMID 38090376, 2023). "In addition, the small-sized PEG-SSNs mediated more tumour accumulation by EPR effect and cellular internalization of siRNA into target cancer cells, resulting in a remarkable inhibition of breast tumour growth via the silencing of EGFR expression in the tumour cells." (PMID 36412852, 2022). "In addition to examining DDA effects on breast tumors with overexpression of wild type EGFR or HER2, in future studies it will be important to determine whether mutants or splice variants of these proteins, such as HER2-delta 16 are responsive to DDAs." (PMID 28423644, 2017). "In addition, EGFR signaling was activated in preM breast tumors." (PMID 26251034, 2015). "In addition, basal breast tumors are characterized by low ER and PR expression as well as high levels of EGFR, elevated expression of AKT3, CD44 and MET and decreased GATA3 expression; features that are also consistent with each of the HER2 related subgroups investigated in the current study." (PMID 21672245, 2011).
breast tumors (continued). "Interestingly, YB-1 was originally isolated as a transcription factor that bound to enhancer sites on the EGFR gene, a finding that could explain, at least in part, why it promotes the growth of breast tumour cells." (PMID 17875215, 2007). "Epidermal growth factor receptor (EGFR) and vascular endothelial growth factor receptor (VEGF) play important role in breast tumor growth, invasion, metastasis, patient survival and drug resistance." (PMID 39405290, 2024). "Calcium apatite NPs-siRNA downregulated BCL-2, EGFR, and ERBB-2 genes, resulting in the cell death-inhibiting PI3K/MAPK signaling pathway in a mouse model of breast tumors." (PMID 36678782, 2023). "Here, we show that neutrophils express among others Siglec-9, and that EGFR and HER2 positive breast tumor cells express ligands for Siglec-9." (PMID 37346044, 2023). "In summary, the presence of α2,3 linked sialic acid on breast tumor cells could be significantly reduced with both neuraminidases and STi, while expression of the target antigens EGFR and HER2 was not affected, which is important for evaluating antibody-mediated effector functions such as ADCC." (PMID 37346044, 2023). "Five estrogen-responsive genes, CYP19A1, EGFR, ESR2, FOS, and IGF1, were found to be modified in human endometriosis, uterine tumor and breast tumor tissues." (PMID 36401252, 2022). "Epidermal growth factor receptor (EGFR) is a glycoprotein, expressed as a transmembrane tyrosine kinase receptor, is studied as a biomarker in TN breast tumours, which can be expressed in 200,000–400,000 receptors in malignant cells." (PMID 36158981, 2022). "TAM was also found to promote CSC phenotype and tumorigenesis in breast cancer by activating the EGFR/Stat3/Sox-2 signaling pathway, while inhibition of Sox2 mitigates TAM mediated induction of CSC phenotype and breast tumor growth." (PMID 34207035, 2021). "Several studies have indicated that overexpression of PRLR, EGFR and HER2 receptors in breast tumors promotes tumor progression via their downstream signaling pathways." (PMID 34572912, 2021). "We describe here a signaling network that relies on EGFR and GPCR activity, converges on the activation of PI3Kβ and operates prevalently in PTEN‐null breast tumor cells." (PMID 32672423, 2020). "The released TGFα-PE38 was then tested in mice with implanted colon or breast tumor cells, which expressed high levels of EGFR (epidermal growth factor receptor)." (PMID 32182799, 2020). "While CNA events in deep or shallow depletion rarely or less occurred, EGFR, MYC, IRF2BP2, ASAP1, and CCT5 (except for DRD1) often underwent copy gain and amplification, acquiring CNA-driven expression in the breast tumors." (PMID 32235890, 2020). "As a dual epidermal growth factor receptor (EGFR)/human EGFR-2 (HER2) tyrosine kinase inhibitor (TKI), lapatinib is approved for use in patients with metastatic HER2-amplified breast tumors." (PMID 31894856, 2020). "We next sought to address the correlation between CNA frequencies and expression levels of MYC, EGFR, ASAP1, IRF2BP2, CCT5, and DRD1 in broad BC cell lines and breast tumors and the clinical relevance of the genes to patients with BC." (PMID 32235890, 2020). "Clinical breast tumor specimens and tumor xenografts were immunolabeled for ERα, PR, HER2, Ki67, CK5/6, EGFR, P120, and E-cadherin." (PMID 30140169, 2018). "The most notable changes are increase in activity of ovulation cycle process (GO:0022602), Epidermal Growth Factor Receptor signalling pathway (EGFR1), and Receptor Activator of Nuclear factor Kappa-B Ligand signalling pathway (RANKL) in ER+ breast tumors." (PMID 29190299, 2017). "Here we show that ERRα in turn regulates tumorigenic processes on stimulation of EGFR/HER2/HER3 signalling, supporting the existence of an ERRα/RTK feed-forward loop further enhancing the mitogenic effect of HER2 in HER2-amplified breast tumours." (PMID 27402251, 2016).
breast tumors (continued). "Recently, TAZ was found to potentiate EGFR signaling in MCF10A cells and play important roles in breast tumor growth and metastasis." (PMID 27167112, 2016). "By integrative functional genomics and molecular cell biological approaches, we showed the involvement of EGFR, RAS, PI3K / AKT, MYC, E2F signaling in the regulation of these selected 1q genes in breast tumors." (PMID 24147022, 2013). "To examine the clinical relevance of this observation, we have generated and analyzed an invasive HBC tissue microarray consisting of 151 breast tumor samples; 79 of which presented a basal-like phenotype (i.e. ER-ve, PR-ve HER2-ve, CK5/6 or EGFR+ve)." (PMID 23721519, 2013). "PTPN12 co-precipitates with several other RTKs and was recently shown to dephosphorylate EGFR and HER2 in breast tumors, thereby inhibiting MAPK signaling." (PMID 23785422, 2013). "EGFR:EGFR homodimers were detected in 5 (27.8%) of the 18 breast tumors, HER2:HER2 homodimers in 12 (66.7%) and EGFR:HER2 heterodimers in 4 tumors (22.2%)." (PMID 22829865, 2012). "For this purpose, we first quantified EGFR and HER2 expression in eighteen breast tumors and confirmed our results using established techniques." (PMID 22829865, 2012). "To assess the suitability of our TR-FRET assays for HER quantification in patients’ samples, we analyzed EGFR and HER2 expression in 18 breast tumors." (PMID 22829865, 2012). "First, EGFR and HER2 expression levels were quantified in 18 breast tumors and the results were compared with those obtained by using reference methods." (PMID 22829865, 2012). "A new version of nanobioconjugate carrying tumor targeting 2C5 mAb and EGFR AON, P/AON/2C5, significantly inhibited breast tumor growth in vivo." (PMID 22355336, 2012). "AEE788 reduced cyclin E in one (of three) kidney tumor cells, which was also inhibited by the dual EGFr and VEGFr inhibitor ZD6474 in breast tumors." (PMID 21867506, 2011). "Based on the ability of Wnt1 to activate EGFR and ERK1/2 signaling in the ER+ T47D and MCF-7 breast tumor cells, we examined the effect of Wnt1 treatment on their response to 4-HT." (PMID 17897439, 2007). "The classification of the breast tumour into the different cell-of-origin subtypes was validated using IHC for ER, PR, ErbB2, EGFR and CK5/6 using a TMA containing core biopsies of each breast tumour in our gene-expression data set." (PMID 17848951, 2007). "In addition, several papers have reported aberrant gene body methylation, including introns in cancer, e.g., hypermethylation of EGFR, LHX2, SOX9, and RFX1 introns in breast tumor tissue compared to paired adjacent tissue." (PMID 37296582, 2023). "However, targeting several other RTKs including the epidermal growth factor receptor (EGFR) and the insulin-like growth factor receptor (IGF1R) in breast tumors has been mostly unsuccessful." (PMID 36568144, 2022). "We believe that overexpression of EGFR/HER2 and PRLR in breast tumors could maximize the actions of their ligands, and further induce cell proliferation promoting malignancy." (PMID 34572912, 2021). "It is a member of the HER family of tyrosine kinase receptors, including three other members [epidermal growth factor receptor (EGFR), HER3, HER4], widely interconnected into a signaling network with important implications in breast oncogenesis and clinical behavior of breast tumors." (PMID 36046143, 2021). "O-NPAT acts on EGFR, which was found to be overexpressed in nearly 15–20% of ER+ tumors, where clinical trials have also shown the efficacy of adjuvant HER2 modulators along with tamoxifen for ER+ breast tumors." (PMID 34122114, 2021). "Given that overexpression of EGFR and ERBB2 by breast tumors predicts a poor prognosis, it might be possible in the future to predict response to IGF1R-directed therapy based on ERBB2/EGFR status." (PMID 32391121, 2020).